TFEB (transcription factor EB)
Diseases named in the same sentence as TFEB in open-access papers (continued):
Sharing a sentence is not in itself a finding about the gene and the disease.
Danon disease (1 paper, 2021). A lysosomal glycogen storage disease characterized by severe cardiomyopathy and variable degrees of muscle weakness, frequently associated with intellectual deficit. "In Danon disease, TFEB and downstream targets are activated." (PMID 33732699, 2021).
depression (1 paper, 2024). "We found that chronic stress altered the morphology of astrocytic lysosomes in the mPFC of susceptible mice, and the protein levels of TFEB and TRPML1 were decreased in depression models." (PMID 39264289, 2024). "In conclusion, our results identify a distinct role of the lysosomal TFEB‐TRPML1 axis in depression through the regulation of lysosomal exocytosis in astrocytes." (PMID 39264289, 2024).
disc degeneration (1 paper, 2024). "In summary, hypoxia‐induced BMSC exosomes deliver BNIP3‐rich vesicles to alleviate disc degeneration by activating the mitochondrial BNIP3/ANXA2/TFEB axis, providing a new target for IVDD treatment." (PMID 38973294, 2024).
eosinophilia (1 paper, 2021). "If TFE3/TFEB are drivers of TSC-RCC, this might explain some of the histologic phenotypes of TSC-RCC, including the eosinophilia, since TFE3/TFEB promote mitochondrial biogenesis." (PMID 34680979, 2021).
epilepsy (1 paper, 2024). A brain disorder characterized by episodes of abnormally increased neuronal discharge resulting in transient episodes of sensory or motor neurological dysfunction, or psychic dysfunction. "The rs4487571 variant in the TFEB host gene, which is a transcription factor that acts as a master regulator of a variety of metabolic and immune pathways, is enriched in white Hispanics with language regression and epilepsy." (PMID 38760502, 2024).
gastric tumor (1 paper, 2022). "We further analyzed TFEB and HPA in gastric tumors using the TCGA database." (PMID 35970822, 2022).
gram-positive bacterial infections (1 paper, 2018). Infections caused by bacteria that retain the crystal violet stain (positive) when treated by the gram-staining method. "In this study, we report that, in addition to its known role in host defense against Gram-positive bacterial infection, TFEB also plays an important role in the intracellular trafficking of a Gram-negative bacillus (GNB), such as A. baumannii, in host cells." (PMID 29600279, 2018). "In this study, we report that, in addition to its known role in host defense against Gram-positive bacterial infection, TFEB also plays an important role in the intracellular trafficking of A. baumannii in host cells." (PMID 29600279, 2018). "During bacterial infection, TFEB and its Caenorhabditis elegans orthologue HLH-30 are regulated by the phospholipase C-protein kinase D (PLC-PKD) pathway and play an important and evolutionary role in the host defense against Gram-positive bacterial infection." (PMID 29600279, 2018).
granulosa cell tumor (1 paper, 2021). A slow-growing, malignant tumor, characterize by the presence of granulosa-like cells and Call-Exner bodies, that is almost always found in the ovary. "TFEB-translocated RCC is typically described as biphasic, with larger epithelioid cells accompanied by a second population of smaller cells, around basement membrane material, reminiscent of Call-Exner bodies in granulosa cell tumors." (PMID 34680535, 2021).
hearing loss (1 paper, 2023). "Autophagic dysfunction-mediated sensory epithelial cell loss and spiral ganglion neuron (SGN) degeneration are induced by inhibition of nuclear migration of TFEB in a model of hearing loss caused by the ototoxic drugs, kanamycin and furosemide." (PMID 38139347, 2023). "Therefore, TFEB may be a target for attenuating SGN degeneration following sensory epithelial cell loss in ototoxic drug-induced hearing loss." (PMID 38139347, 2023).
Hypoglycemia (1 paper, 2023). A decreased concentration of glucose in the blood. "Surprisingly, however, TFEB/TFE3‐deficient mice, despite showing a massive increase in INS mRNA levels, do not show hypoglycemia but instead are glucose intolerant, suggesting that lack of TFEB and TFE3 may affect β‐cell function and insulin production at different levels." (PMID 37712288, 2023).
intestinal infection (1 paper, 2022). "Transcription factors ELT-2 and TFEB are known to act in tissue-specific manner and regulate defence responses during intestinal infection of nematodes with bacteria." (PMID 36344922, 2022).
invasive breast carcinoma (1 paper, 2021). A carcinoma that infiltrates the breast parenchyma. "A higher TFEB and Beclin-1 expression correlate with shorter survival in patients with chemo-treated invasive breast cancer (respectively HR 3.46, CI.95 1.27–9.47, p < 0.05 and 7.11, CI.95 2.54–19.9)." (PMID 34663249, 2021).
ischemia reperfusion injury (1 paper, 2025). Adverse functional, metabolic, or structural changes in ischemic tissues resulting from the restoration of blood flow to the tissue (reperfusion), including swelling; hemorrhage; necrosis; and damage from free radicals. "In 2015, Rebecca Godar claimed that intermittent fasting in adult C57BL/6 mice triggered autophagy by nuclear translocation of TFEB, which started the autophagy-lysosome machinery and protected cardiac ischemia-reperfusion injury." (PMID 40028479, 2025).
ischemic disease (1 paper, 2020). Lack of blood supply to an area of the body, resulting in impairment of tissue oxygenation. "In addition, transcription factor EB activates the transcription of ALKBH5 and downregulates the stability of METTL3 mRNA in hypoxia/reoxygenation-induced autophagy in ischemic diseases." (PMID 31931709, 2020).
kidney (1 paper, 2018). "In contrast, TFEB remained cytosolic in MVO-treated MEF and in AEP-null kidney PTC." (PMID 30559339, 2018).
kidney injury (1 paper, 2020). Trauma to the kidney. "Innovation and conclusion: Our data suggest that trehalose treatment preserves mitochondria function via activation of TFEB-mediated autophagy and attenuates cisplatin-induced kidney injury." (PMID 32483422, 2020).
large cell lung carcinoma (1 paper, 2025). "We also observed the effect of GK on TFEB in another NSCLC subtype, large cell lung carcinoma (LCC), for which limited information regarding its relationship with TFEB is available in databases." (PMID 40083935, 2025).
lentivirus infection (1 paper, 2022). Virus diseases caused by the Lentivirus genus. "TFEB overexpression by lentivirus infection effectively increased the mRNA and protein levels of TFEB." (PMID 35082964, 2022).
lipomatosis (1 paper, 2023). A neoplastic process characterized by diffuse overgrowth of mature adipose tissue. "The lipomatosis could be either a direct effect of the PRDM10 variant, for example by gene expression changes other than FLCN reduction, or it may be an adipose tissue-specific effect of folliculin repression and downstream TFE3/TFEB activation, which is described to play a role in adipose tissue." (PMID 36440963, 2023).
lung disease (1 paper, 2020). "Additional mechanistic evidence comes from a study that showed bleomycin directly binds to annexin A2 (ANXA2) in lung epithelial cells, thereby preventing the nuclear translocation of TFEB; thus, there is an inhibition of the autophagy flux resulting in fibrotic lung disease pathogenesis." (PMID 32847034, 2020).
lupus (1 paper, 2020). "Our research has shown a consistent lysosomal malfunctioning in lupus splenocytes, manifested in the increase in endo/lysosomal volume, loss of acidification, reduced proteolytic activity against endocytosed substrates and TFEB expression." (PMID 33092174, 2020).
meningoencephalitis (1 paper, 2023). Inflammation of the meninges and brain, generally secondary to an infectious cause. "Coxsackievirus B3, a virus associated with myocarditis and meningoencephalitis In children, targets TFEB for proteolytic processing to disrupt host lysosomal function by affecting lysosomal biogenesis signalling." (PMID 37317179, 2023).
Merkel cell carcinoma (1 paper, 2024). "Conversely, a more recent study found that upregulation of TFEB in Merkel cell carcinoma led to increased expression of HLA-ABC in tumor cells." (PMID 39349845, 2024).
metabolism (1 paper, 2021). "Transcription factor EB (TFEB) is a master transcriptional regulator of lysosomal biogenesis and autophagy and, when activated, is effective against disorders of lipid metabolism." (PMID 34366846, 2021).
metastatic melanoma (1 paper, 2019). A melanoma that has spread from its primary site to another anatomic site. "In metastatic melanomas TFEB and TFE3 positively correlate with the expression of genes required for the immune response." (PMID 30705290, 2019).
Myocardial fibrosis (1 paper, 2023). "In the context of myocardial fibrosis, TFEB inhibited cell migration and collagen I concentration at the cellular level." (PMID 37609444, 2023).
neoplasm of the bile ducts (1 paper, 2025). "The regions showing neoplasm of the bile ducts showed nuclear TFEB, TFE3, and SOX9, and hyperactivation of mTORC1 as evidenced by immunostaining for the phosphorylated S6 protein of the 40S ribosomal subunit (P-S6), used as readout of mTORC1 activity." (PMID 40189703, 2025).
nutritional deficiency (1 paper, 2021). "To find out the specific mechanism by which apigenin regulates TFEB, we focused on the AMPK pathway, a key metabolic sensor of regulating autophagy, which was activated by nutritional deficiency or increased AMP/ATP ratio." (PMID 35096819, 2021).
ovarian diseases (1 paper, 2024). "Since TFEB was recently discovered to be a potential therapeutic target for alleviation of myocardial ischemic injury and neurodegeneration, we were interested in its role in regulating the autophagy-lysosome pathway in ovarian diseases." (PMID 38383507, 2024).
pediatric renal cell carcinoma (1 paper, 2011). "Notably, two other members of the MiT family of basic-helix-loop-helix/leucine zipper transcription factors, TFE3 and TFEB, have been recurrently affected by translocations that result in the upregulation of these transcription factors in human pediatric renal cell carcinoma." (PMID 22039523, 2011).
primary immunodeficiencies (1 paper, 2025). "The data suggest a potential implication of IFT20 and TFEB defects in diseases characterized by impaired CTL function, of which prominent ones are primary immunodeficiencies and cancer." (PMID 40389449, 2025).
proliferative diabetic retinopathy (1 paper, 2025). Advanced retinopathy due to diabetes mellitus characterized by the formation of new vessels in the retina. "Among the TFEB-footprinted genes, we also identified genetic targets involved in the regulation of cell migration in sprouting angiogenesis and in the negative regulation of vasculature development, which have clinical relevance in proliferative diabetic retinopathy and neovascular AMD." (PMID 40565279, 2025).
pterygium (1 paper, 2020). A wedge-shaped fibrovascular lesion arising from the bulbar conjunctiva and extending to the cornea. "mTORC1 regulates autophagy by inhibiting ULK and the nuclear translocation of transcription factor EB (TFEB) and suppresses apoptosis in pterygium by controlling Beclin1-dependent autophagy by targeting Bcl-2." (PMID 33256738, 2020).
pulmonary lymphangioleiomyomatosis (1 paper, 2021). "Here we show that lysosomal biogenesis is increased in TSC-associated renal tumors, pulmonary lymphangioleiomyomatosis, kidneys from Tsc2+/− mice, and TSC1/2-deficient cells via a TFEB-dependent mechanism." (PMID 34253722, 2021).
renal oncocytoma (1 paper, 2022). "This would include renal oncocytoma, eosinophilic variant of chromophobe RCC, succinate dehydrogenase (SDH)-deficient RCC, MiTF translocation RCC (particularly TFEB), and epithelioid angiomyolipoma (AML)." (PMID 35203531, 2022).
Sandhoff disease (1 paper, 2021). A lysosomal disorder from the GM2 gangliosidosis family, caused by biallelic pathogenic variants in the HEXB gene, characterized by GM2 ganglioside accumulation in the nervous system and progressive central nervous system degeneration. "As to the upstream drive to enhance autophagosome genesis in Tay–Sachs and Sandhoff diseases, we find evidence that this is due to nuclear translocation of TFEB, since it activates genes that orchestrate lysosomal biogenesis." (PMID 34831346, 2021).
sarcoidosis (1 paper, 2020). Sarcoidosis is a multisystemic disorder of unknown cause characterized by the formation of immune granulomas in involved organs. "For instance, transcription factor EB (TFEB), a master regulator of lysosomal biogenesis and fusion was significantly downregulated in sarcoidosis AMs in response to DEX." (PMID 32477331, 2020).
skin cancer (1 paper, 2019). "UVA irradiation also activates transcription factor EB (TFEB) and upregulates expression of p62 as well as cyclooxygenase-2 (COX-2), a prostaglandin synthase implicated in skin cancer development." (PMID 31417903, 2019).
Thrombocytopenia (1 paper, 2025). A reduction in the number of circulating thrombocytes. "More recently, the first direct TFEB inhibitor, eltrombopag, has been approved for the treatment of thrombocytopenia." (PMID 40779629, 2025).
tongue squamous cell carcinoma (1 paper, 2022). A squamous cell carcinoma that arises from the tongue. "A recent study shows that TFEB suppression in tongue squamous cell carcinoma line reduces Pt tolerance." (PMID 35053335, 2022).
type 1 diabetes (1 paper, 2019). "A recent study in cardiomyocytes has found reduced TFEB expression in both a mouse model of type 1 diabetes (Akita mice) and in obese patients." (PMID 30710421, 2019).
ZIKV infection (1 paper, 2022). "The expression of lysosomal lipase is regulated by TFEB, which was significantly upregulated upon ZIKV infection." (PMID 36405969, 2022). "ZIKV infection increased the levels of TFEB, which is a key regulator of lysosomal biogenesis and promotes autophagosome-lysosome fusion." (PMID 36405969, 2022).
tumor (165 papers, 2014 to 2026). "Urolithins, produced from ellagic acid, induce mitophagy in tumor-associated macrophages (TAMs) via transcription factor EB (TFEB) activation while expanding CD8+ T memory stem cells through Pink1-mediated mitochondrial regulation." (PMID 41181090, 2025). "The silencing of TFEB also changed the susceptibility to apoptosis of cancer cells and the tumor immune micro-environment (TIME) qualitative and quantitative composition, as indicated by the scRNA-Seq analysis of the immuno-xenografts." (PMID 39107857, 2024). "TFEB is associated with tumor progression and promotes various cancer phenotypes by regulating the autophagolysosomal system, even in an autophagy-independent manner." (PMID 38926803, 2024). "By supplementing BCAA catabolism, the tumour inhibitory effect caused by TFEB knockdown can be significantly reversed." (PMID 38938061, 2024). "Mechanistically, UA inhibits TFEB ubiquitination-mediated degradation and enhances TFEB nuclear translocation in tumor-associated macrophages, thereby promoting the transcriptional activation of mitophagy-related genes regulated by TFEB." (PMID 39472438, 2024). "Compared with the adjacent normal tissues, the expression of TFEB was significantly increased in the BC tissues (P<0.05), suggesting that TFEB expression was associated with the tumor progression of BC." (PMID 37885995, 2023). "Accordingly, transcription factor EB (TFEB) modulates tumor-associated macrophage (TAM) gene expression in BC through several pathways, for example, by promoting NLRP3 inflammasome degradation." (PMID 34064909, 2021). "The first is that activation of mTOR regulates the upstream of autophagy to cause tumor more sensitive, while TFEB regulates the downstream lysosomal fusion to promote tumor progression." (PMID 34830772, 2021). "A study reported that TFEB is a master regulator of tumor-associated macrophages in the breast TME, downregulation of TFEB-induced macrophage polarization and a tumor-promoting phenotype." (PMID 33732651, 2021). "Other components of the tumor microenvironment, including tumor‐associated macrophages, have been implicated in tumor promotion through the expression of TFEB." (PMID 31304632, 2019). "Recent advances have expanded understanding of TRIM37 function, linking it to mTORC1 TFEB signalling autophagy, centrosome integrity, extracellular matrix regulation, and immune cell function, providing mechanistic insights into tumour predisposition, skeletal pathology, and immune dysregulation." (PMID 42123650, 2026). "Such atypical FLCN‐mutated tumours exhibit diverse morphologies and additional molecular alterations (for example, a concomitant TFEB gain/amplification), and typically lack the mosaic (‘hybrid’) cell morphology and IHC profiles seen in the typical FLCN‐mutated tumours." (PMID 41384711, 2026). "TFEB itself is assumed as a key regulator of autophagy, which is functionally linked to tumor development, and therefore, discussed as a putative target of novel tumor therapy." (PMID 39851496, 2025). "Furthermore, in breast cancer tumor-associated macrophages TFEB modulates anti-tumor immune response." (PMID 39107857, 2024). "After enrichment, some pathways were associated with biological dysfunction and abnormal behavior caused by aberrant overexpression of TFEB genes, such as E-cadherin, an essential regulator of tumor cell-to-cell interactions, lysosomal biogenesis, and autophagy of tumor cells." (PMID 38730456, 2024). "Moreover, the gain of 6p is associated with higher tumor grades, advanced tumor stages, and upregulation of the TFEB protein." (PMID 37533434, 2023). "Finally, TFEB co-deletion restored the defects of FlcnΔDC mice in controlling tumour growth, which were associated with a reversal of CD8+ T cell accumulation defects." (PMID 37407815, 2023).